MGMT (O-6-methylguanine-DNA methyltransferase)
Diseases named in the same sentence as MGMT in open-access papers (continued):
Sharing a sentence is not in itself a finding about the gene and the disease.
glioblastoma (continued). "Subsequent studies support MGMT promoter methylation as a predictive biomarker in glioblastoma, but the exact role in guiding clinical management is still being refined, partly due to challenges in testing methodology and establishing meaningful cutoffs for the assays." (PMID 30967140, 2019). "MiR-198 restored the tumor sensitivity to TMZ in glioblastomas overexpressing MGMT." (PMID 32010632, 2019). "A Pubmed literature search independently conducted by the first and the last author using the keywords “MGMT AND glioblastoma AND relapse”, “O6-methylguanine DNA methyltransferase AND glioblastoma AND relapse” and “MGMT AND methylation AND change” was performed latest on 30 October 2019." (PMID 31766430, 2019). "In glioblastoma multiforme patients, high MGMT expression is associated with temozolomide resistance, while tumor cells lacking MGMT activity are more sensitive to alkylating agents." (PMID 31581233, 2019). "Thus, methylation in promoter MGMT gene was observed in matched tissue and serum ctDNA from glioblastoma patients as well as correlated with clinical response to therapy." (PMID 31284524, 2019). "Biomarkers that influence clinical management include IDH mutations, combined with loss of chromosome arms 1p and 19q, leading to a diagnosis of oligodendroglioma that responds well to PCV, whereas methylation of the MGMT promoter in glioblastoma predicts a better response to TMZ." (PMID 31747973, 2019). "Therefore, we used pyrosequencing, which is a quantitatively accurate method that is already in clinical use for assessment of MGMT methylation levels in glioblastoma." (PMID 29495584, 2018). "Promoter methylation of MGMT is now clinically used in the management of glioblastoma multiforme." (PMID 30416678, 2018). "Even at this early stage of the molecular understanding of glioblastoma, statistically significant correlations are seen between our imaging subtypes and the four molecular subtypes, as well as EGFRvIII and IDH1 mutation status, and MGMT methylation status." (PMID 29572492, 2018). "It is worth mentioning a currently ongoing individualized screening trial of innovative glioblastoma therapy (INSIGhT) designed as a randomized, multi-arm phase II trial for patients with newly diagnosed glioblastoma and unmethylated MGMT promoter (NCT02977780)." (PMID 30563098, 2018). "Since glioblastoma patients receiving Stupp’s regimen having an unmethylated MGMT promoter present shorter PFS and OS, this may also explain the shorter PFS of patients with ELMO3 hypomethylation." (PMID 29495584, 2018). "Expression of MGMT in glioblastoma or melanoma is a marker for resistance to TMZ in the clinic." (PMID 30416678, 2018). "Importantly, these different impacts of MGMT status on overall survival were similarly observed in newly diagnosed glioblastoma patients, elderly glioblastomas and recurrent glioblastomas." (PMID 30279357, 2018). "MGMT-methylated glioblastoma respond better to DNA alkylating chemotherapy with improved prognosis." (PMID 29732009, 2018). "MGMT-methylations status is relevant for glioblastoma, as it could aid patient selection for adjuvant temozolamide chemotherapy." (PMID 29732009, 2018).
glioblastoma (continued). "Our study reports a significant negative impact of higher doses of radiation received by normal stem cells on OS in a homogeneous subgroup of patients with IDH-wild-type glioblastoma, whilst taking into account MGMT promoter methylation status and EGFR amplification." (PMID 30338243, 2018). "The MGMT promoter status has been shown to predict response to alkylating agents in glioblastoma patients, and in times of personalized and precision medicine even such low case numbers could be of clinical significance." (PMID 29445424, 2018). "A diagnosis of IDH-WT glioblastoma was made, and the MGMT promoter was found to be unmethylated." (PMID 30305059, 2018). "Our data also indicate that ALDH3A1 may regulate TMZ sensitivity in glioblastoma cells independently of the MGMT promoter methylation status." (PMID 29854309, 2018). "Thus, most of the IDH-mutant glioblastomas are MGMT promoter methytlated: patients with IDH1mut and MGMTunmet or IDH1WT and MGMTmet or IDH1WT and MGMTWT." (PMID 30279357, 2018). "In a cell line study, rs1625649 alone could downregulate the MGMT promoter activity in the transfected glioblastoma cells." (PMID 29036186, 2017). "Within hypermethylated c-HMRs, we detected previously reported frequent DNA hypermethylation at gene promoters such as MGMT in glioblastoma, NSD1 in neuroblastoma, ESR1 in breast cancer, GSTP1 in prostate cancer and the promoter hypermethylation of RASSF1 in various cancer contexts." (PMID 28581523, 2017). "Moreover, glioblastoma patients with high MGMT expression show poorer prognosis than those with low or negative expression." (PMID 28346397, 2017). "In the neuro-oncological field, reference histology and molecular marker evaluation with O-6-methylguanine-DNA-methyltransferase (MGMT) promoter methylation are now widely used for molecular analysis of glioblastoma for inclusion in clinical trials (e.g. Centric, Glarius)." (PMID 28101701, 2017). "Overall, our findings suggest that carmustin wafer implantation in combination with maximal safe resection, followed by combined standard chemoradiation protocols, is a promising treatment option for patients with supratentorial glioblastoma harboring MGMT promoter methylation." (PMID 28484518, 2017). "As DNA methylation and DNA repair are two targeted aspects of antitumor effect for the alkylating chemotherapeutic agent TMZ, the expression of DNA repair enzyme MGMT and removal of methyl residue in GSCs were suggested as underlying the chemo-resistance against TMZ of glioblastomas." (PMID 28415586, 2017). "As radiation is delivered in 1.8–2 Gy daily dose fractions over 6 weeks with daily temozolomide for patients with glioblastoma, a daily IV dosing schedule may be feasible to attain sustained MGMT silencing during this period." (PMID 28752860, 2017). "The identification of MGMT as the key player in the resistance to chemotherapy in glioblastoma, and the fact that it serves not only as prognostic but also as predictive factor, have made this enzyme a potential target for personalized therapy and facilitated the development of several inhibitors." (PMID 28976305, 2017). "They further reported that level of global DNA methylation was proportional to MGMT promoter methylation in gliomas and that higher level of global DNA methylation was a favorable prognostic factor in primary glioblastoma, even compared to MGMT promoter methylation." (PMID 28968983, 2017). "This approach holds direct translational significance in glioblastoma and brain metastases where radiation is part of the standard of care; our approach to silence MGMT could overcome the significant problem of MGMT-mediated chemoresistance." (PMID 28752860, 2017). "Patients with glioblastoma containing a methylated MGMT promoter can benefit from TMZ." (PMID 28955297, 2017).
glioblastoma (continued). "Specifically, MGMT methylation was seen in 39–53% of CRCs, 11% of gastric cancer, 30–38% of lung cancer, 34–72% of esophageal cancer, 34% of soft tissue sarcomas, 58% of breast cancer, and 30–70% of glioblastoma." (PMID 27643594, 2016). "First, we showed that HRM correlates with the MGMT activity in glioblastoma cell lines." (PMID 27158275, 2016). "Moreover, clonal analysis of glioblastoma samples demonstrated inter-tumor variability in MGMT promoter methylation and MGMT protein expression levels, which were inconsistent with TMZ responses." (PMID 27158244, 2016). "The most important clinical biomarker used for glioblastoma is MGMT promoter methylation status." (PMID 26940435, 2016). "For example, MGMT methylation is common, but KRAS mutations are relatively rare in glioblastoma." (PMID 27643594, 2016). "In addition, promoter methylation of the O-6-methylguanine-DNA methyltransferase (MGMT) has been shown to be predictive of response to alkylating agents in glioblastoma." (PMID 27835597, 2016). "However, there are still other factors that affected the prognosis for the glioblastoma patients with similar MGMT methylation status." (PMID 27588397, 2016). "In glioblastoma patients, however, also DNA repair mechanisms other than MGMT may modify the temozolomide response." (PMID 27556305, 2016). "As the protein acts independently from MGMT expression status of the tumor cells, it might become a useful substance in the treatment of glioblastoma multiforme." (PMID 27275537, 2016). "Validation in experimental glioblastoma cell models in vitro supported the bioinformatics analyses and indicated that downregulation of MGMT expression by miR-181d-5p and miR-767-3p is due to degradation of the MGMT mRNA whereas miR-648 affects MGMT protein translation." (PMID 27057640, 2016). "We checked MGMT mRNA expression in three glioblastoma cell lines, namely T98G, U251 and U373." (PMID 27057640, 2016). "The MGMT status of 139 glioblastoma patients, whom had received standard first line treatment, was determined using pyrosequencing (PSQ) and a semi-quantitative Methylation-specific PCR (sqMS-PCR) method, using both frozen and formalin-fixed paraffin-embedded FFPE samples." (PMID 27542245, 2016). "This study evaluates whether delays in chemo-radiotherapy after surgery, while determining O6-methylguanine-DNA-methyltransferase (MGMT) promoter status, affect the survival rates of patients with glioblastoma (GBM)." (PMID 26223282, 2015). "Moreover, MGMT promoter methylation is correlated with improved response to TMZ in glioblastoma patients." (PMID 26400193, 2015). "MGMT is over-expressed by many glioblastomas and inactivates TMZ." (PMID 26702034, 2015). "Therefore, identifying a new strategy to sensitize the MGMT-expressing GSC to clinically achievable dose of TMZ in brain will have important implications for the management of glioblastoma patients with unmethylated MGMT promoter." (PMID 26546412, 2015). "A fourth major contribution was obtained by testing significant reduction of MGMT protein expression with a genome-wide miR screening performed by transfecting 885 known miRs into the T98G glioblastoma cell line, which is characterized by high levels of the MGMT protein." (PMID 26035292, 2015). "Validation in glioma tissues ex vivo and in experimental glioblastoma cell models in vitro supported the bioinformatics analyses and indicated that downregulation of MGMT expression by miR-181d and miR-767-3p is due to degradation of the MGMT mRNA whereas miR-648 affects MGMT protein translation." (PMID 26035292, 2015). "Several recent studies show that MGMT pyrosequencing is a robust technique that offers valid, reliable and quick evaluation of the MGMT promoter methylation status from formalin-fixed and paraffin-embedded glioblastoma specimens and is therefore a rational candidate method for clinical purposes." (PMID 26295302, 2015).
glioblastoma (continued). "The expression level of MGMT and the methylation status of the MGMT gene promoter might have a predictive value in patients with glioblastoma treated with alkylating drugs such as temozolomide." (PMID 25908947, 2015). "Finally, we also studied the methylation of MGMT promoter, as it has been shown in previous studies that methylation was much more frequently found in long-term survivors than in general glioblastoma population." (PMID 26158269, 2015). "Another important biomarker in glioblastoma involves MGMT promoter methylation (methMGMT)." (PMID 26503470, 2015). "Here we used MGMT-expressing glioblastoma stem cells (GSC) lines as a model for investigating the molecular mechanism underlying TMZ resistance, while aiming to explore a new treatment strategy designed to possibly overcome resistance to the clinically relevant dose of TMZ (35 μM)." (PMID 26546412, 2015). "Furthermore, the MGMT status determined by pyrosequencing was shown to correlate with progression-free and overall survival of glioblastoma patients in several independent patient cohorts." (PMID 24359605, 2014). "Since the MGMT promoter methylation status is the most established predictive marker of glioblastoma survival, we evaluated whether treatment efficacy was related to this factor." (PMID 25568669, 2014). "The MGMT status of the glioblastoma cells is involved in responsiveness to TMZ." (PMID 24678590, 2014). "For instance, an MGMT promoter unmethylated glioblastoma may harbor low MGMT expression as a result of high miR-181d or miR-603 expression." (PMID 24994119, 2014). "Furthermore, molecular markers like MGMT hypermethylation and IDH1 mutation seem to play a growing role as predictors for prognosis and therapeutic response in glioblastoma patients." (PMID 24758192, 2014). "MGMT promoter methylation and clinical outcomes in Chinese glioblastoma patients*." (PMID 25211033, 2014). "MGMT was one of the first predictive DNA methylation biomarkers to determine a patient’s response to alkylating chemotherapeutics and it was shown that glioblastoma patients with tumor MGMT promoter methylation have a survival benefit from Temozolomide chemotherapy." (PMID 25229548, 2014). "Extent of MGMT promoter methylation and clinical outcome in Chinese glioblastoma patients*." (PMID 25211033, 2014). "Therefore, MGMT promoter methylation testing allowed the visualization of a promising future for highly individualized management of glioblastoma patients." (PMID 24454798, 2014). "We feel that the confirmation of the high analytical performance of MGMT pyrosequencing is of major relevance for the care of glioblastoma patients, as it allows implementation of MGMT testing for prognostic and especially predictive purposes in the clinical setting." (PMID 24359605, 2014). "However, reports on the correlation between MGMT and clinical outcomes in Chinese glioblastoma patients are very scarce." (PMID 25211033, 2014). "Thus, pyrosequencing-based assessment of MGMT promoter methylation status in glioblastoma meets the criteria of high analytical test performance and can be recommended for clinical application, provided that strict quality control is performed." (PMID 24359605, 2014). "Furthermore, MGMT promoter methylation was demonstrated to result in decreased MGMT expression and correlates with a survival benefit in glioblastoma patients treated with alkylating chemotherapeutics such as temozolomide." (PMID 24380367, 2013). "Thus, we focused on establishing new pyrosequencing assays for the analysis of the methylation status of the ABCB1 and the ABCG2 promoter in a collective of 64 glioblastoma patients using MGMT promoter methylation as reference." (PMID 24380367, 2013).
glioblastoma (continued). "To investigate whether the expression levels of MGMT and NTN4/ITGB4 are associated in glioblastoma tissues, we analyzed the expression levels of primary tumors from The Cancer Genome Atlas - Glioblastoma multiforme (TCGA-GBM) repository." (PMID 24265816, 2013). "Methylation of the MGMT promoter may be detected in 60% of glioblastomas, although the false-positive rate is high." (PMID 23946790, 2013). "We then evaluated the expression of MGMT and miR-221 in human glioblastoma samples." (PMID 24147153, 2013). "However MGMT is frequently silenced by promoter hypermethylation in several tissues, such as bone marrow, and up to 75% of high-grade glioblastomas." (PMID 24019948, 2013). "We have developed a novel method for double-labelling for MGMT, which is quick and easy to apply and might readily be subsumed into routine reporting for glioblastomas (and other tumours)." (PMID 24252243, 2013). "Glioblastoma patients with high expression of MGMT have usually minimal response to temozolomide." (PMID 24265816, 2013). "Primary glioblastoma patients with a methylated MGMT promoter (as evaluated by both methylation detection methods) had approximately 5 months longer median survival compared to patients with an unmethylated promoter (log-rank test; pyrosequencing P = .02, qMSP P = .06)." (PMID 22390413, 2012). "A high expression rate of MGMT protein in glioblastomas may be related to a more indolent disease phenotype." (PMID 22214427, 2012). "Furthermore, the MGMT status has been prospectively validated in a phase III trial as biomarker for favorable outcome in glioblastoma patients treated with temozolomide." (PMID 22810491, 2012). "This review will address the challenges and ways in which we can improve our discovery and translation of prospective biomarkers from the lab into validated diagnostic tests with a specific focus on patients diagnosed with glioblastoma and MGMT promoter methylation status." (PMID 23346075, 2012). "Hence, the MGMT status is widely determined in most clinical trials and frequently requested in routine diagnostics of glioblastoma." (PMID 22428052, 2012). "Nevertheless, based on the observations done here, it could be argued that a primary glioblastoma should be regarded MGMT promoter methylated if the pyrosequencing result is positive." (PMID 22390413, 2012). "It is evident that glioblastomas exhibit molecular heterogeneity involving EGFRvIII and PTEN mutations, increased AKT activation, or MGMT promoter methylation that may differentiate the efficiency of EGFR-AKT-mTOR cascade targeting among patients." (PMID 22530122, 2012). "For the model, however, this may generate a bias in the estimation of MGMT methylation probabilities based on the MGMT-STP27 model for non-glioblastoma tumors." (PMID 22810491, 2012). "Evaluation of MGMT mRNA expression was possible in 41/44 (93.2%), of MGMT protein expression in 35/44 (79.5%), and of MGMT promoter methylation status in 23/44 (52.3%) of the glioblastoma cases with available tissue blocks." (PMID 22214427, 2012). "Hence, the MGMT methylation status has become a biomarker used for patient stratification or patient selection in clinical trials for glioblastoma patients." (PMID 22810491, 2012). "RECQ1 expression is also not related to the methylation status of the MGMT gene which identifies a subgroup of glioblastoma more susceptible to the cytotoxic effect of temozolomide treatment." (PMID 21752281, 2011). "Indeed, in glioblastoma clinical trials, a strong correlation of the methylation status of MGMT with temozolomide response and patient outcome was shown." (PMID 21269507, 2011). "In order to test if there was any relationship between RECQ1 expression and MGMT status, we investigated the methylation status of the MGMT gene promoter region in the subgroup of RECQ1 positive primary glioblastomas characterized by a staining nuclear intensity value in IHC of 3+." (PMID 21752281, 2011).